MIR302B (microRNA 302b)
Synonyms: hsa-mir-302b; MIRN302B; mir-302b
Gene: MicroRNA gene on chromosome 4 (112,648,485 to 112,648,557, reverse strand). Ensembl gene ENSG00000284463.
Gene Ontology:
Biological process: miRNA-mediated post-transcriptional gene silencing
Cellular component: RISC complex
Homologues: Orthologues: chimpanzee ptr-mir-302b (100% identical), macaque mml-mir-302b (96% identical), rabbit MIR302B (89% identical), dog MIR302B (88% identical), guinea pig MIR302B (81% identical), tropical clawed frog xtr-mir-302 (64% identical). Paralogues in human: MIR302D (71% identical), MIR302A (68% identical), MIR302C (67% identical).
Diseases named in the same sentence as MIR302B in open-access papers:
MIR302B is named in the same sentence as 1 disease in open-access papers, as found by Europe PMC text mining. Sharing a sentence is not in itself a finding about the gene and the disease.
MIR302B shares sentences with these, for which no sentence is quoted: cancer (1 paper).